PCBP4 (poly(rC) binding protein 4)
Description:
Single-stranded nucleic acid binding protein that binds preferentially to oligo dC.
Synonyms: MCG10; LIP4; CBP
Tractability: PROTAC: ubiquitination databases record sites on it; its protein half-life has been measured.
Gene: Protein-coding gene on chromosome 3 (51,957,448 to 51,974,016, reverse strand). Ensembl gene ENSG00000090097.
Subcellular location: Cytoplasm
Subcellular location (Human Protein Atlas): Cytosol
Pathways (Reactome):
Gene expression (Transcription): FOXO-mediated transcription of cell cycle genes
Cell Cycle: Transcriptional activation of cell cycle inhibitor p21
Gene Ontology:
Molecular function: mRNA 3'-UTR binding; protein binding; RNA binding; nucleic acid binding
Biological process: regulation of mRNA stability; negative regulation of mRNA splicing, via spliceosome; regulation of transcription by RNA polymerase II; regulation of gene expression; regulation of mRNA metabolic process
Cellular component: cytosol; cytoplasm
Genetic constraint (gnomAD): Loss-of-function variants: 24 observed, 46.73 expected, observed/expected ratio (o/e) 0.51, 90% interval 0.37 to 0.72. The upper end of that interval is the gene's LOEUF score, 0.72, which puts it in group 2 of 6, group 1 being the genes least tolerant of losing a copy. Missense variants: 407 observed, 545.77 expected, observed/expected ratio (o/e) 0.75, 90% interval 0.69 to 0.81. Synonymous variants: 203 observed, 230.51 expected, observed/expected ratio (o/e) 0.88, 90% interval 0.79 to 0.99.
Homologues: Orthologues: chimpanzee PCBP4 (100% identical), macaque PCBP4 (99% identical), pig PCBP4 (98% identical), dog PCBP4 (98% identical), rabbit PCBP4 (98% identical), rat Pcbp4 (98% identical), guinea pig PCBP4 (98% identical), mouse Pcbp4 (98% identical), zebrafish pcbp4 (63% identical), Drosophila melanogaster mub (46% identical), Caenorhabditis elegans pes-4 (30% identical), Drosophila melanogaster ps (21% identical), and 5 more. Paralogues in human: PCBP3 (48% identical), PCBP2 (47% identical), PCBP1 (45% identical), FUBP1 (27% identical), KHSRP (27% identical), FUBP3 (25% identical), IGF2BP2 (25% identical), HNRNPK (24% identical), IGF2BP3 (23% identical), IGF2BP1 (23% identical), NOVA1 (21% identical), NOVA2 (21% identical).
Diseases named in the same sentence as PCBP4 in open-access papers:
PCBP4 is named in the same sentence as 12 diseases in open-access papers, as found by Europe PMC text mining. Sharing a sentence is not in itself a finding about the gene and the disease. The quoted sentences say what the papers report.
lung carcinoma (3 papers, 2013 to 2015). "We selected PCBP4 as the candidate of the target gene to examine resistance to cisplatin because PCBP4 reportedly induces cell cycle arrest in G2/M in some lung cancer cells." (PMID 26196957, 2015). "PCBP4 (MCG10) can induce apoptosis and may function as a lung tumor suppressor and its expression can inhibit the proliferation and tumorigenesis of lung cancer cells, both in vivo and in vitro, by delaying the progression of the cell cycle." (PMID 24026233, 2013).
head and neck cancer (1 paper, 2015). A primary or metastatic malignant neoplasm affecting the head and neck. "PCBP4 is a novel molecular target for the therapy of head and neck cancers, especially cisplatin-resistant cancers." (PMID 26196957, 2015). "In our study, inhibition of PCBP4 decreased cisplatin resistance in head and neck cancer cells, which suggests that PCBP4 is a major component of cisplatin resistance and a new target for treatment of HNSCC, by enhancement of the effects of chemo-radiotherapy with cisplatin." (PMID 26196957, 2015). "Regimens based on inhibitors that are selective for PCBP4 might be particularly promising in cases for which therapeutic treatments for advanced head and neck cancers beyond surgery have had limited success to date." (PMID 26196957, 2015).
maxillary cancer (1 paper, 2015). "PCBP4 plays important roles in the induction of cisplatin resistance in human maxillary cancers." (PMID 26196957, 2015).
cancer (4 papers, 2015 to 2023). A tumor composed of atypical neoplastic, often pleomorphic cells that invade other tissues. "Interestingly, the most significantly upregulated genes in Ppm1dT/+ AML (Zbed3, Runx3, Marcks, Extl3, Pcbp4, Igf2bp3, Plch1, and Gdf6) were previously associated with AML and cancer progression." (PMID 37709843, 2023).
tumor (3 papers, 2015 to 2020). "In addition, PCBP4 silencing significantly inhibited tumor sphere formation, while the tumor sphere area of the NT control cells did not decrease upon MDK inhibition (p < 0.5 and p < 0.01 for shPCBP4-1 and -2, respectively)." (PMID 31811117, 2019). "Because of the potential risk of spontaneous tumor generation, we also suggest the development of strategies to simultaneously block PCBP4-associated tumorigenic molecules such as ZFP87141 in the suppression of PCBP4 in vivo." (PMID 31811117, 2019).
infection (1 paper, 2016). The state of being infected such as from the introduction of a foreign agent such as serum, vaccine, antigenic substance or organism. "For example, two stress response genes, SSRP1, PCBP4, (and 6 other validated examples of proximal polyadenylation site usage after the infection produced shorter transcripts." (PMID 27354008, 2016).
PCBP4 also shares sentences with these, for which no sentence is quoted: atherosclerosis (1 paper); breast carcinoma (1); cholesterol ester storage disease (1); Niemann-Pick disease type C (1); retinal degeneration (1); schizophrenia (1).